MAGEC1 (MAGE family member C1)
Synonyms: CT7.1; MAGE-C1; CT7; MGC39366
Tractability: PROTAC: ubiquitination databases record sites on it.
Gene: Protein-coding gene on chromosome X (141,903,894 to 141,909,374, forward strand). Ensembl gene ENSG00000155495.
Subcellular location: Cytoplasm
Subcellular location (Human Protein Atlas): Cytosol; Nucleoplasm
Gene Ontology:
Molecular function: protein binding
Biological process: negative regulation of transcription by RNA polymerase II
Cellular component: cytoplasm; nucleus
Homologues: Orthologues: rat Magea13 (10% identical), mouse Magea13 (10% identical), zebrafish ndnl2 (6% identical), Drosophila melanogaster MAGE (5% identical). Paralogues in human: MAGEC2 (19% identical), MAGEC3 (17% identical), MAGEA10 (15% identical), MAGEA11 (12% identical), MAGEA9 (12% identical), MAGEA9B (12% identical), MAGEA4 (12% identical), MAGEA8 (12% identical), MAGEB4 (12% identical), MAGEB18 (12% identical), MAGEB10 (12% identical), MAGEB17 (12% identical), and 25 more.
Diseases named in the same sentence as MAGEC1 in open-access papers:
MAGEC1 is named in the same sentence as 38 diseases in open-access papers, as found by Europe PMC text mining. Sharing a sentence is not in itself a finding about the gene and the disease. The quoted sentences say what the papers report.
myeloma (21 papers, 2011 to 2025). "MAGEC1 (Melanoma Antigen Family C, 1) is a protein coding gene associated with myeloma, digestive tract carcinomas, glioblastoma and melanoma." (PMID 26822197, 2016). "MAGEC1 helps cancer cells in multiple myeloma to escape from immune-surveillance, and its expression stimulates proliferation of cancer cells." (PMID 26822197, 2016). "MAGE family member C1 (MAGEC1) has close links to melanoma and myeloma development." (PMID 40957660, 2025).
melanoma (11 papers, 2010 to 2025). A malignant, usually aggressive tumor composed of atypical, neoplastic melanocytes. "It is noteworthy that two proteins namely MAGEC1 (Melanoma antigen family c1) and FCRL1 (Fc receptor-like 1), which were known for melanoma progression were up-regulated in metastatic melanoma." (PMID 28302167, 2017). "We undertook a mutational analysis of coding regions of four CT-X MAGE genes, MAGEA1, MAGEA4, MAGEC1, MAGEC2 and the ubiquitously expressed MAGEE1 in human melanoma samples." (PMID 20862285, 2010).
breast cancer (5 papers, 2013 to 2024). A primary or metastatic malignant neoplasm involving the breast. "However, no humoral response was observed against SSX-4, MAGE-3, MAGEC1 and MAGEC2 in breast cancer." (PMID 23451156, 2013).
metastatic melanoma (3 papers, 2011 to 2023). A melanoma that has spread from its primary site to another anatomic site. "A recent study investigated MAGEC1 expression in primary and metastatic melanoma, reporting the predisposition of MAGEC1-positive patients to metastasize, with a significantly higher number of lymph node metastases." (PMID 37047539, 2023).
gastric cancer (2 papers, 2018 to 2022). A primary or metastatic malignant neoplasm involving the stomach. "The amplificated CNV of immune‐related genes in gastric cancer tissues was accompanied by the increase of their mRNA level (e.g., LRRN3 and NFATC2), and vice versa (e.g., MAGEC1)." (PMID 34582114, 2022).
glioblastoma (2 papers, 2011 to 2016). The most malignant astrocytic tumor (WHO grade IV). "Similarly in MAGEC1 Ile1001 (corresponding to Met214 in yeast Nse3) was mutated to Phe in glioblastoma multiforme cells." (PMID 21364888, 2011).
schizophrenia (2 papers, 2023 to 2024). A major psychotic disorder characterized by abnormalities in the perception or expression of reality. "Sporadic variants in MAGEC1 (MIM# 300223) are well documented in patients with DD, schizophrenia, and, notably, ASD." (PMID 39519104, 2024).
glioma (1 paper, 2025). A benign or malignant brain and spinal cord tumor that arises from glial cells (astrocytes, oligodendrocytes, ependymal cells). "MAGEA11 and MAGEC1 were hypermethylated in AR-negative gliomas (Kruskal–Wallis < 0.05) as well as in IDH-mutant low-grade tumors." (PMID 41153666, 2025).
mesothelioma (1 paper, 2016). A usually malignant and aggressive neoplasm of the mesothelium which is often associated with exposure to asbestos. "The region of the MAGEC1 promoter exhibits high levels of methylation and the gene is lowly expressed in TCGA mesothelioma tumors." (PMID 26848772, 2016).
ovarian tumors (1 paper, 2023). "Lower levels of mRNA expression of genes of the 21 CTAs in ovarian tumors were detected for CTAG1A, CTAG1B, MAGEC1, and PIWIL2." (PMID 37835834, 2023).
synovial sarcoma (1 paper, 2022). "Immunohistochemical staining for MAGEC1, a protein, that is, found in intracellular complexes with CTAG1B/A, showed extensive (80%) positivity in synovial sarcoma cells in one of seven cases evaluated, whereas the remaining six cases were negative." (PMID 35664317, 2022).
cancer (28 papers, 2006 to 2025). A tumor composed of atypical neoplastic, often pleomorphic cells that invade other tissues. "These variants were found in genes associated with cancers (ANKRD35, DNAH9, MAGEC1, TOX3) or participating in cancer-related signaling pathways (THSD1, MORN2, PTCRA)." (PMID 26822197, 2016). "Three of these mRNAs encode cancer testes antigens (NY-ESO-1, MAGEC1, and MAGEC2) which are normally only expressed in male germ cells but are often also expressed in tumors including NSCLC, making them an attractive target for cancer vaccines." (PMID 25288198, 2014). "The expression of MAGEC1 is frequently elevated in a variety of cancers." (PMID 24618420, 2014). "Notably, LIHC, KIRC, and OV cancers had the 40 same upregulated genes, such as FOXJ1, LOC100128674, MAGEC1, and PAGE2." (PMID 35813444, 2022). "While extensive interactions between MAGE family genes such as MAGEA9, MAGE9B, MAGEB6 and MAGEC1 correspond to the cancer subtypes BLCA, HNSC and LUSC, interactions between Zinc fingers C2H2-type proteins in the downregulated components characterized COAD and READ cancer subtypes." (PMID 34728699, 2021).
tumor (26 papers, 2011 to 2025). "Melanoma-associated antigen C1 (MAGEC1) is a potential target in immunotherapy because its expression is present only in tumor cells." (PMID 37047539, 2023). "First, we found multiple MAGE family proteins (e.g., MAGEC2, MAGEB2, MAGEC1, MAGEB6) with a gene expression profile similar to those in clinical trials (MAGEA1, MAGEA4), which have been reported to be tumor specific." (PMID 39515334, 2024). "The examination indicated the hub genes in tumor samples, including GAGE2A, GAGE1, MAGEA9, CTAG1A, CTAG1B, and MAGEA1; and the hub genes in healthy ovarian tissue samples, including SPA17, MAGEC1, KDM5B, SSX4, and MAGEA9." (PMID 37835834, 2023). "Two DEGs were identified for both the Group B/trastuzumab-sensitive models (tumor-specific antigens CTAG1B, MAGEC1) and the Group C/all treatment-sensitive models (HLA-DRB5, RNL5)." (PMID 37749105, 2023). "These CTAs were expressed by tumor cells, similar to MAGEA10, MAGEC1, and CTAG1B proteins as demonstrated in our previous study." (PMID 34065388, 2021). "The analysis of the mRNA expression levels of 21 CTAs in healthy and tumor ovarian tissue showed an up-regulation in the expression level of AKAP3, MAGEA4, PIWIL1, and PRAME in tumor samples and a down-regulation in the expression level of CTAG1A, CTAG1B, MAGEC1, and PIWIL2." (PMID 37835834, 2023).
MAGEC1 also shares sentences with these, for which no sentence is quoted: multiple myeloma (12 papers); lung carcinoma (4); esophageal squamous cell carcinoma (3); non-small cell lung carcinoma (3); ovarian carcinoma (3); prostate carcinoma (3); acute myeloid leukemia (2); cutaneous melanoma (2); lymph node metastases (2); mucosal melanoma (2); amyloidosis (1); anal melanoma (1); Cirrhosis (1); extramedullary plasmacytoma (1); head and neck squamous cell carcinoma (1); hepatocellular carcinoma (1); invasive breast carcinoma (1); lung adenocarcinoma (1); Lung squamous cell carcinoma (1); mast cell leukemia (1); monoclonal gammopathy of undetermined significance (1); nodular sclerosis (1); osteosarcoma (1); small cell lung carcinoma (1); thyroid cancer (1).